HES3 (hes family bHLH transcription factor 3)
Description:
Transcriptional repressor of genes that require a bHLH protein for their transcription.
Synonyms: bHLHb43
Tractability: No criterion of Open Targets' tractability assessment is met for any kind of drug.
Gene: Protein-coding gene on chromosome 1 (6,244,179 to 6,245,578, forward strand). Ensembl gene ENSG00000173673.
Subcellular location: Nucleus
Subcellular location (Human Protein Atlas): Nucleoplasm
Gene Ontology:
Molecular function: DNA-binding transcription factor activity, RNA polymerase II-specific; RNA polymerase II cis-regulatory region sequence-specific DNA binding; protein dimerization activity
Biological process: anterior/posterior pattern specification; negative regulation of transcription by RNA polymerase II; regulation of neurogenesis
Cellular component: chromatin; nucleus
Genetic constraint (gnomAD): Loss-of-function variants: 9 observed, 8.47 expected, observed/expected ratio (o/e) 1.06, 90% interval 0.64 to 1.75. That is too few expected variants to judge how well the gene tolerates losing a copy. Missense variants: 266 observed, 206.1 expected, observed/expected ratio (o/e) 1.29, 90% interval 1.17 to 1.43. Synonymous variants: 121 observed, 87.97 expected, observed/expected ratio (o/e) 1.38, 90% interval 1.19 to 1.6.
Homologues: Orthologues: chimpanzee HES3 (98% identical), macaque HES3 (89% identical), pig HES3 (74% identical), guinea pig HES3 (73% identical), dog HES3 (72% identical), mouse Hes3 (64% identical), rat Hes3 (61% identical), tropical clawed frog hes3 (43% identical), zebrafish her3 (34% identical), Drosophila melanogaster E(spl)mbeta-HLH (24% identical), Drosophila melanogaster E(spl)mgamma-HLH (24% identical), Drosophila melanogaster E(spl)m3-HLH (23% identical), and 6 more. Paralogues in human: HES1 (29% identical), HES4 (28% identical), HES7 (25% identical), HEY2 (25% identical), BHLHE40 (25% identical), BHLHE41 (23% identical), HEY1 (23% identical), HES2 (22% identical), HELT (22% identical), HEYL (22% identical), HES6 (21% identical), HES5 (20% identical).
Diseases named in the same sentence as HES3 in open-access papers:
HES3 is named in the same sentence as 17 diseases in open-access papers, as found by Europe PMC text mining. Sharing a sentence is not in itself a finding about the gene and the disease. The quoted sentences say what the papers report.
brain cancer (2 papers, 2010 to 2013). A primary or metastatic malignant neoplasm affecting the brain. "Recently, we have also shown that the presence of Hes3 marks not only the normal endogenous NSC but also the stem cell compartment in malignant brain tumors." (PMID 20520777, 2010).
glioblastoma (2 papers, 2010 to 2025). The most malignant astrocytic tumor (WHO grade IV). "The first studied system encompassed patient-derived glioblastoma cell lines cultured in conditions supporting different levels of activation of the STAT3-Ser/Hes3 signaling axis involved in cancer growth regulation." (PMID 39960760, 2025). "Similarly, in human biopsies from Grade IV Glioblastoma multiforme, Hes3 is found in both the cytoplasm and nucleus." (PMID 20520777, 2010).
rhabdomyosarcoma (2 papers, 2018 to 2024). A rare aggressive malignant mesenchymal neoplasm arising from skeletal muscle. "While dysregulation of HES3 was observed in children with fusion-positive rhabdomyosarcoma, the precise mechanism of HES3 involvement in this pediatric cancer remained unclear." (PMID 38611039, 2024). "Overall, this new PAX3-FOXO1 zebrafish model of rhabdomyosarcoma identifies her3/HES3 as a mediator of tumorigenesis." (PMID 29869612, 2018). "Taken together, these data are consistent with our results showing that her3/HES3 is a PAX3-FOXO1 target, and that HES3 contributes to a more aggressive phenotype in rhabdomyosarcoma." (PMID 29869612, 2018). "Human rhabdomyosarcoma tumors with high HES3 levels were also more likely to have certain cell-growth and cell-differentiation related proteins." (PMID 29869612, 2018). "Ectopic expression of the her3 human ortholog, HES3, inhibits myogenesis in zebrafish and mammalian cells, recapitulating the arrested muscle development characteristic of rhabdomyosarcoma." (PMID 29869612, 2018). "Our novel zebrafish rhabdomyosarcoma model identifies a new PAX3-FOXO1 target, her3/HES3, that contributes to impaired myogenic differentiation and has prognostic significance in human disease." (PMID 29869612, 2018). "To determine if HES3 overexpression confers properties indicative of tumorigenic capacity in cell culture systems, we analyzed HES3’s impact on C2C12 mouse myoblasts and human rhabdomyosarcoma cells." (PMID 29869612, 2018). "We examined a panel of rhabdomyosarcoma cell lines and have observed low HES3 levels by RNAseq, and no detectable endogenous HES3 protein expression with commercially available antibodies (data not shown)." (PMID 29869612, 2018). "Chip-seq data from rhabdomyosarcoma cell culture indicates that PAX3-FOXO1 does not bind the HES3 promoter; however, these results may differ in a dynamic developmental context." (PMID 29869612, 2018).
diabetes (1 paper, 2018). "We establish Hes3 as a biomarker to monitor the brain in animal models that are widely used to study various aspects of diabetes mellitus." (PMID 30054579, 2018). "This work suggests that Hes3 is a valuable biomarker helping to monitor the state of endogenous neural stem and progenitor cells in the context of diabetes mellitus." (PMID 30054579, 2018). "Our data establish Hes3 as a potentially valuable biomarker for the impact of diabetes on the plasticity potential of the brain." (PMID 30054579, 2018). "Our observation that Hes3 expression in the brain drops with age might have important connotations in diabetes mellitus." (PMID 30054579, 2018). "As described in the introduction, we hypothesized that brain Hes3 expression would be altered in mouse models of diabetes, in which insulin signaling is perturbed." (PMID 30054579, 2018). "Future studies will address whether Hes3 is also regulated in diabetes patients, which parameters of insulin deregulation and/or diabetes mellitus are primarily responsible for Hes3 regulation, and the roles that Hes3 plays in the progression of diabetes-related phenotypes." (PMID 30054579, 2018). "Therefore, one could expect that the combination of a high-Hes3 young brain and elevated Hes3 expression due to diabetes mellitus could impact the stem cell-rich cytoarchitecture of the hippocampus." (PMID 30054579, 2018).
embryonal carcinoma (1 paper, 2018). A non-seminomatous malignant germ cell tumor characterized by the presence of large germ cells with abundant cytoplasm resembling epithelial cells, geographic necrosis, high mitotic activity, and pseudoglandular and pseudopapillary structures formation. "Antibody 2448 was found to specifically bind to HES-3 (hESC) and 2102Ep (embryonal carcinoma cells) but not on normal adult cell lines: HFF (human foreskin fibroblast), IMR90 (lung fetal fibroblast) and HEK293 (human embryonal kidney)." (PMID 29568351, 2018).
teratoma (1 paper, 2018). A non-seminomatous germ cell tumor characterized by the presence of various tissues which correspond to the different germinal layers (endoderm, mesoderm, and ectoderm). "A closer look at the expression patterns from these teratoma samples revealed higher expression of neuroectodermal markers in KhES-1 and HES3 MIXL1GFP/w compared to all other lineages and lower expression of endodermal markers in Shef3 compared with the other lineages." (PMID 29765017, 2018).
type 1 diabetes (1 paper, 2018). "Hes3 null mice are more sensitive to pancreatic islet damage by the toxin streptozotocin (STZ; used to model type 1 diabetes), compared to wild type (WT) mice, and regenerate beta cell mass less efficiently." (PMID 30054579, 2018).
type 2 diabetes (1 paper, 2018). "Our data show that streptozotocin-induced β-cell damage, high fat diet, as well as metformin, a common type 2 diabetes medication, regulate Hes3 levels in the brain." (PMID 30054579, 2018). "Future work may address the mechanisms by which Hes3 is regulated in the animal models we employed, as well as, potentially in patients with type 1 and type 2 diabetes, and during metformin administration." (PMID 30054579, 2018).
cancer (7 papers, 2010 to 2025). A tumor composed of atypical neoplastic, often pleomorphic cells that invade other tissues. "These cells, which are marked by molecules such as CD24, CD44, CD133, and Hes3, have the ability to self-renew and differentiate into more mature cancer cells, aiding in tumor progression and the formation of pseudopalisading necrosis." (PMID 40223032, 2025). "In cancer, HES3 is expressed in glioblastoma cell culture, and co-localizes with additional markers of stemness in the mouse brain." (PMID 29869612, 2018). "In line with this notion, putative cancer stem cells from the aggressive brain tumor glioblastoma multiforme express Hes3 both in the patient and in culture." (PMID 24101906, 2013). "These treatments support the self renewal state of cultured NSCs and expression of the transcription factor Hes3, which also identifies the cancer stem cell population in human tumors." (PMID 20195471, 2010). "Uncovering novel treatments that will affect Hes3 expression and localization will be a new set of tools in regenerative and cancer medicine." (PMID 20520777, 2010).
tumor (5 papers, 2018 to 2025). "The expression of HES3 was linked with the pro-tumorigenic events in mammalian cells, which are also linked with the tumor progression and reduced survival in patients with RMS tumors; thus, HES3 could be a novel target for RMS treatment." (PMID 37958442, 2023).
neurodegenerative disease (1 paper, 2012). A disorder of the central nervous system characterized by gradual and progressive loss of neural tissue and neurologic function. "It will be of great value to extend these results in order to determine if Hes3+ cells participate in the neurogenic programs of the adult hippocampus and to assess their significance in models of neurodegenerative disease, learning, and memory." (PMID 23251599, 2012).
HES3 also shares sentences with these, for which no sentence is quoted: glomerular disease (1 paper); glomerulosclerosis (1); hypospadias (1); infantile hemangiomas (1); Insulin resistance (1); insulinoma (1).